IL6 (interleukin 6)
Diseases named in the same sentence as IL6 in open-access papers (continued):
Sharing a sentence is not in itself a finding about the gene and the disease.
Cognitive impairment (continued). "Future experiments that seek to inhibit microglial activation or the production of specific cytokines, such as IL-6, may better inform the specific function of microglia and the molecules they produce in the associated cognitive deficits measured here." (PMID 28973966, 2017). "In the current study, plasma IL-6 levels were associated with self-perceived cognitive impairment." (PMID 27701469, 2016). "Hence, one would expect to observe higher plasma IL-6 levels among patients who are carriers of the G allele, and the resultant increase in IL-6 levels would be associated with cognitive impairment." (PMID 27701469, 2016). "We also identified that higher serum IL-6 levels can be independently predictive of MHE, which may support that IL-6 had a more robust association with cognitive impairment in liver cirrhosis." (PMID 26039496, 2015). "In addition, both high IL-6 and its increase were associated with greater risk of cognitive impairment." (PMID 26289439, 2015). "A long-term study (over 20 years) indicated that repeated high or increasing IL-6 was associated with cognitive impairment; CRP alterations were inconsistent with cognition, which may involve impacts of statin medications and survival effects." (PMID 26682220, 2015). "We now appreciate that inflammatory cytokines may be influenced by habitual behavior; this includes Interleukin-6 (IL-6), an inflammatory cytokine strongly associated with cognitive impairment, functional decline, loss of strength, sarcopenia, and mortality." (PMID 21899733, 2011). "Targeted deletion of IL-6 or elimination of superoxide by chronic treatment with a superoxide-dismutase mimetic prevented age-related loss of PV-interneurons and reversed age-related cognitive deficits on three standard tests of spatial learning and recall." (PMID 19436757, 2009). "This association would indicate that persistently elevated levels of IL-6 generate an inflammatory environment that structurally alters specific brain regions, with an inverse correlation between peripheral inflammatory markers and brain region volume, which is associated with cognitive deficits." (PMID 40650149, 2025). "Potential mechanisms discussed in current literature that may underlie the link between IL-6 levels and cognitive deficits include the neurodegenerative effects of elevated IL-6 levels and its association with blood-brain barrier dysfunction and subsequent cognitive impairment." (PMID 41323348, 2025). "This association between neuroinflammation and long-term cognitive impairment suggests that there may be a similar role for IL-6 in the development of cognitive impairment that occurs after surgery, which are known collectively as Perioperative Neurocognitive disorders (PND)." (PMID 36778590, 2022). "It has not been evaluated if the cholinergic system, the neurotransmitter system most affected in AD, is impaired in this model, and it is important to understand if IL-6 induced inflammation may cause cholinergic system degeneration and contribute to cognitive impairment." (PMID 25025046, 2014). "Thus, the association between IL-6 serum increases and deficits in verbal memory obligates us to explore the cognitive consequences of an inflammatory imbalance and cognitive impairment in highly exposed cohorts." (PMID 24133408, 2013). "Thus, while elevated systemic cytokines, in particular IL-6, are clearly a risk factor for delirium, and severity of acute insult is a predictor of delirium generally, prior cognitive impairment is a crucial cofactor and thus pre-existing pathology is likely to be the key risk factor." (PMID 20471138, 2012). "Because treatments which lower plasma IL-6 levels and/or block IL-6 signaling are currently in clinical use for other indications, these agents could be used to test idea that lowering IL-6 may preserve in the integrity of the PV-inhibitory system and prevent associated cognitive deficits." (PMID 19436757, 2009).
Cognitive impairment (continued). "In recent epidemiologic studies, peripheral IL-6 levels showed an inverse correlation with cognitive function in aged subjects, with chronic elevation of peripheral IL-6 associated with mild cognitive deficits, even in apparently healthy community-living older adults." (PMID 19436757, 2009). "Several studies have shown that suppressing the production of IL-6 results in neuroinflammatory decline, attenuation of behavioral dysfunction, and cognitive impairment." (PMID 41557677, 2026). "Bacillus subtilis administration prevented cognitive deficits, maintained Tnfa at control levels, and significantly reduced Il1b and Il6 expression compared to the LPS + ZDV group." (PMID 41892682, 2026). "In these studies, increased IL-6 levels were found in patients with cognitive deficits or post-acute sequelae." (PMID 41516418, 2026). "These cognitive deficits are thought to be driven by chronic hypoxemia and impaired cerebral perfusion, systemic inflammation involving IL-6, TNF-α and CRP, and cardiovascular comorbidities frequently coexisting in COPD." (PMID 41598607, 2026). "Upon administration, LPS activates microglia and astrocytes, which trigger pro-inflammatory modulators (IL-1β, IL-6, and TNF-α), causing the progression of neurological complications such as cognitive impairment." (PMID 41557677, 2026). "In this regard, a relevant observation is the consistency of the elevation of inflammatory cytokines IL-6, IL-13, IL-8, IL-1β, and TNFα at the longest phase of follow-up related to cognitive deficits and/or post-acute sequelae." (PMID 41516418, 2026). "When comparing studies using chemotherapy in healthy versus tumor-bearing animal models, both groups exhibited a consistent pattern of cognitive impairment accompanied by increased levels of pro-inflammatory cytokines, particularly IL-1β, IL-6, and TNF-α." (PMID 41155372, 2025). "And higher IL-6 levels were predictive of subsequent conversion to mild cognitive impairment (MCI) and a greater accumulation of Aβ over a two-year period." (PMID 40103929, 2025). "Advanced age and preexisting cognitive impairment, major risk factors for POD, are linked to chronic low-grade inflammation (“inflammaging”), which includes elevated IL-6 levels." (PMID 40951922, 2025). "While associations between elevated inflammatory markers (e.g., IL-6, TNF-α) and cognitive impairments have been observed, direct evidence establishing neuroinflammation as a primary cause of LDs is still limited." (PMID 40150106, 2025). "These microbial shifts are associated with increased neuroinflammatory cytokines, such as interleukin-1β (IL-1β), interleukin-6 (IL-6), and tumor necrosis factor-alpha (TNF-α), which have been implicated in synaptic plasticity and cognitive deficits." (PMID 40881681, 2025). "On the other hand, the levels of tumor necrosis factor (TNF)-α and interleukin 6 (IL-6) were significantly higher in MHD patients with cognitive impairment." (PMID 40950978, 2025). "Because neuroinflammation contributes to cognitive impairment, we evaluated the effects of the combined mulberry leaves and butterfly pea flower extract on interleukin-6 (IL-6) levels in the prefrontal cortex and hippocampus." (PMID 40868955, 2025). "Ursolic acid can also inhibit the activation of microglia and astrocytes and reduce the levels of TNF–α, IL–1β, and IL–6 in the brain inflammation of mice with lipopolysaccharide–induced cognitive deficits." (PMID 40005889, 2025). "Excessive sleep duration can lead to elevated neuroinflammation levels, including increased levels of proinflammatory factors (e.g., C‐reactive protein and interleukin 6), which is one of the crucial mechanisms for cognitive impairment." (PMID 39692596, 2025). "This study linked elevated inflammatory markers, specifically IL-6 and sTNF-RII, with cognitive impairments post-hematopoietic cell transplantation (HCT)." (PMID 39982240, 2025).
Cognitive impairment (continued). "It has been shown that ketamine inhibits pro-inflammatory cytokines such as interleukin-6 (IL-6) and tumor necrosis factor-alpha (TNF-α), which have been linked with cognitive impairment." (PMID 40809865, 2025). "IL-6 overexpression is a hallmark of neuroinflammation, indicating that PM2.5 induces the hypomethylation of the IL-6 promoter, resulting in IL-6 overexpression and the promotion of neuroinflammation, thus leading to cognitive impairment in sub-rats." (PMID 39997934, 2025). "Recent studies have highlighted the role of pro-inflammatory cytokines such as TNF-α and IL-6 not only in cognitive impairments but also in mood disturbances among COVID-19 survivors." (PMID 41268373, 2025). "Among inflammatory markers, interleukin-6 (IL-6) and tumour necrosis factor-alpha (TNF-α) have been linked to both psychosis pathophysiology and related cognitive impairments." (PMID 40637145, 2025). "Multiple studies have reported elevated TNF⍺, IL6, IL1β, and hyperactive microglia in AD patients with early mild cognitive impairment (MCI), contributing to LTP impairment via Aβ-induced proinflammatory cytokines." (PMID 40498003, 2025). "Increased IL-6 expression disrupts the balance between inhibitory and excitatory synapses through both the classical and trans-IL-6 signaling pathways, impairing inhibitory synapse functionality and ultimately contributing to cognitive impairment." (PMID 41301474, 2025). "In rodent models, IL-6 plays a crucial role in the affective and cognitive impairments resulting from social stress." (PMID 37314479, 2025). "Dysregulated cytokine release, including elevated levels of tumor necrosis factor-alpha (TNF-α), interleukin-1β (IL-1β), and interleukin-6 (IL-6), exacerbates neuronal injury and cognitive impairment." (PMID 40822471, 2025). "A recurring finding was the elevation of pro-inflammatory cytokines (i.e., IL-1β, IL-6, TNF-α) together with reduced BDNF levels, frequently associated with cognitive deficits in both healthy and tumor-bearing models." (PMID 41155372, 2025). "Specifically, we observed increased levels of the pro-inflammatory cytokines IL-6, TNF-α, and CXCL1, all of which have been implicated in cognitive impairments associated with AD." (PMID 41282256, 2025). "Consistent with links between senescence and cognitive impairment, we found inverse correlations between time spent exploring Y maze's open arm and the frequency of p21, Il1α and Il6 positive cells in the hippocampus." (PMID 39374134, 2025). "The first aim of this study was to assess the mediating effect of IL-6 in the association between T2DM and biomarkers of neurodegeneration and cognitive impairment." (PMID 40606939, 2025). "Anesthesia/surgery-induced blood–brain barrier disruption and cognitive deficits are strongly age-dependent, and systemic IL-6 knockout significantly mitigates these postoperative impairments." (PMID 40914484, 2025). "Studies observed altered peripheral IL-6 levels in patients with mild cognitive impairment and AD dementia, but this evidence was less strong for CSF IL-6." (PMID 38336728, 2024). "The possible mechanism underlying such cognitive impairment is the effect of inflammatory cytokines triggered by SARS-CoV-2 infection, mainly interleukin-6 (IL-6) and tumor necrosis factor-α (TNF-α)." (PMID 38336659, 2024). "IL-6 has been identified as a blood marker of cognitive decline and severity of cognitive impairment." (PMID 39148685, 2024). "Neuroinflammation featured by the overactivation of glial cells, robustly produced a body of neuroinflammatory factors, including TNF‐α, IL‐6, IL‐1β and NO, etc., and subsequently led to neuronal damage and cognitive impairment." (PMID 37697966, 2024). "This is surprising as postsurgical studies in elderly patients found plasma TNFα, IL-6, and IL-10 levels to be independent predictors for adverse central postoperative outcomes such as cognitive deficits." (PMID 38585987, 2024).
Cognitive impairment (continued). "Multiple cytokines stem from activated platelets and regulate platelet function in the pathogenesis of cognitive impairment, such as IL-1 and interleukin-6 (IL-6)." (PMID 38709763, 2024). "The severity of cognitive impairment correlated with plasma IL-1β and TNFα levels and serum IL-6 levels." (PMID 39769285, 2024). "Interleukin-6 (IL-6), tumor necrosis factor-a (TNF-a), and C-reactive protein have been shown to be linked to cognitive impairment, and changes in peripheral CD4+, CD8+, CD3+, and CD4+/CD3+ levels have been documented." (PMID 38322584, 2024). "We noticed that cytokines IL-1β, TNF-α and IL-6 changes were rapid but transient, while C3 upregulation was delayed but prolonged, a pattern that concur more with the time course of cognitive deficits." (PMID 38427092, 2024). "IL-6 was particularly higher in both the very severe and the moderate with cognitive impairment groups, than the mild group." (PMID 37368949, 2024). "In the AD and mild cognitive impairment (MCI) groups, IL-6 and TNF-a were likewise positively associated." (PMID 38230738, 2024). "In brain homeostasis, IL-6 is present in low concentrations, but during CNS infection elevated IL-6 levels are responsible for memory and cognitive impairment." (PMID 39772122, 2024). "Such a study showed also a correlation between serum IL-10 levels and the severity of tremor and higher serum IL-6 levels in patients with ET and cognitive impairment." (PMID 39769168, 2024). "Daytime changes were positively correlated with IL-2 (r = 0.462, P = 0.030), IL-6 (r = 0.516, P = 0.017), and IL-8 (r = 0.462, P = 0.030) levels, and there was a positive correlation between cognitive disorder scores and IL-6 levels (r = 0.492, P = 0.023)." (PMID 38877455, 2024). "QCLG improved weight loss, cognitive impairment, neurological function scores, blood ammonia, and brain gene expression of interleukin-6 (TNF-α), Interleukin-1β (IL-1β), and interleukin-6 (IL-6) induced by HE." (PMID 39220284, 2024). "IL-6 and CRP levels are associated with cognitive impairment, executive function, and attention/working memory." (PMID 37762207, 2023). "This evidence converges to support the association of cognitive impairment in schizophrenia with GMV reduction and increases in the IL-6 level." (PMID 37838729, 2023). "Regardless of various arguments in the literature, earlier meta-analyses revealed that the IL-6 levels are raised in both cerebrospinal fluid (CSF) and mild cognitive impairment (MCI) plasma and in patients with AD in comparison to control persons." (PMID 37376007, 2023). "Cognitive impairment, represented by reduced place recognition memory that is accompanied by hippocampal upregulation of mRNA levels of IL-1β, IL-6, and TNF-α, has also been recently observed in HFD and fiber-deficient diet mice." (PMID 37432552, 2023). "In the same way that IL-6 is altered in patients with cognitive impairment, a recent review found that CRP is also involved in this mechanism." (PMID 37251808, 2023). "In a meta-analysis of 41 studies, it was reported that IL-6 and CRP levels were consistently increased in all stages of schizophrenia, and elevated CRP was associated with more cognitive impairment." (PMID 37763110, 2023). "Other authors reported that IL-6 concentration in CNS-enriched exosomes was increased in patients with cognitive impairment, as compared to healthy controls." (PMID 37511589, 2023). "Furthermore, several potential explanations for the association between BMD and cognitive impairment are as follows: First, bone mass loss may cause an increase in certain inflammatory markers, such as interleukin-6 and TNF-α, which promote the accumulation of inflammatory plaques in the brain." (PMID 37107586, 2023). "The production of proinflammatory cytokines, such as TNF‐α, IL‐6, and IL‐1β, further aggravates the neuroinflammatory response and leads to cognitive disorder." (PMID 37550899, 2023).
Cognitive impairment (continued). "Several mechanisms underlying these effects have been proposed, but few studies have involved the examination of associations among IL-6 levels, GMV alterations in the frontal lobe and hippocampus, and cognitive impairment in such patients." (PMID 37838729, 2023). "Increased IL-6 and CD70 were associated with cognitive impairment, highlighting the role of CD70 in neuroinflammation in the CNS." (PMID 37445634, 2023). "Elevations in proinflammatory cytokines, including IL-6, have been demonstrated in patients with orthostatic intolerance, fatigue and cognitive impairment." (PMID 36992793, 2023). "It has been shown that IL-1β and IL-6 play roles in regulating cognitive function; blocking IL-1β in AD mouse models protects against cognitive deficits, and the upregulation of IL-6 contributes to cognitive deficits in humans." (PMID 34958017, 2022). "More importantly, hyperforin treatment significantly reduced Aβ deposition, GFAP expression, levels of IFN-γ, IL-1β, IL-6, and TNFα, and improved performance in behavioral tests, suggesting reversal of cognitive deficits." (PMID 35077394, 2022). "Overall, the results suggested that peripheral IL-6 contributed to CNS neuroinflammation and cognition impairment in delirium." (PMID 36160165, 2022). "A previous study suggested that the levels of CRP, TNF-α, IL-1β, IL-6, and IL-8 in the peripheral blood of patients with mild cognitive impairment (MCI) were higher than those in the normal population." (PMID 36590060, 2022). "We found that SCH58261 inhibited microglial activation and decreased the levels of TNF-α, IL-1β and IL-6, ultimately alleviating cognitive impairment in CP mice." (PMID 36234803, 2022). "In summary, IL-6 is positioned to mediate vulnerability to postoperative cognitive impairment in aging and AD and possibly to drive longer term neurodegenerative changes that can further exacerbate postoperative cognitive decline." (PMID 36778590, 2022). "Neuronal-derived EV proteins have been shown to differ depending on cognitive impairment status, including IL-6, in veterans with remote TBI." (PMID 35528741, 2022). "In surgical model, we found that BBB was disrupted by the increasing level of IL-6 and thus induced cognitive impairment, especially in old mice with higher serum level of IL-6 than young mice with that." (PMID 36353359, 2022). "The M1‐type macrophage further releases the proinflammatory cytokines such as IL‐1β, TNF‐α, and IL‐6, thereby resulting in brain damage and cognitive impairment." (PMID 34951130, 2022). "There was a significant positive, very high linear correlation between the level of interleukin 6 (r = 0.788, *p < 0.05), TNFα (r = 0.817, *p < 0.05) in prefrontal cortex and cognitive impairment in diabetics mice in Y Maze Novelty Preference Test (NPT)." (PMID 35468904, 2022). "TNF-α and IL-6 were negatively associated with MMSE score, and high TNF-α, IL-1β, and IL-6 were correlated with cognition impairment occurrence." (PMID 35239774, 2022). "Increased levels of central IL-6 have been shown to mediate disease behaviors, including lethargy, insanity, and cognitive deficits." (PMID 36466655, 2022). "Simultaneously, other research does not find a strict positive correlation between the severity of positive symptoms, cognitive deficits and enhanced levels of proinflammatory cytokines, such as IL-6, IL-1β and TNF-α." (PMID 36139363, 2022). "Pretreatment with i.c.v. sgp130Fc, the selective blocker of IL-6 trans-signaling, prevented postoperative cognitive impairment and pSTAT3 upregulation in the hippocampus." (PMID 36778590, 2022). "Several epidemiologic studies have shown a rather consistent association between systemic inflammatory markers (i.e., high-sensitivity C-reactive protein, tumor necrosis factor-alpha, and interleukin-6) and dementia or cognitive impairment." (PMID 35160273, 2022).